ADPGK-AS1 (ADPGK antisense RNA 1)
Gene: Long non-coding RNA gene on chromosome 15 (72,782,835 to 72,798,201, forward strand). Ensembl gene ENSG00000260898.
Diseases named in the same sentence as ADPGK-AS1 in open-access papers:
ADPGK-AS1 is named in the same sentence as 3 diseases in open-access papers, as found by Europe PMC text mining. Sharing a sentence is not in itself a finding about the gene and the disease. The quoted sentences say what the papers report.
gastric cancer (1 paper, 2024). A primary or metastatic malignant neoplasm involving the stomach. "The upregulation of adenosine diphosphate-dependent glucose antagonist RNA 1 (ADPGK-AS1) in the adenosine diphosphate-dependent glucose (ADPGK) family of genes increases in gastric cancer tissues and cell lines." (PMID 39765609, 2024).
tumor (1 paper, 2025). "Significantly, macrophage-specific ADPGK-AS1 knockdown reverts cells to tumor-suppressive M1-like states, inhibiting tumor progression across preclinical models." (PMID 41409273, 2025).
ADPGK-AS1 also shares sentences with these, for which no sentence is quoted: cancer (1 paper).